IL1B (interleukin 1 beta)
Diseases named in the same sentence as IL1B in open-access papers (continued):
Sharing a sentence is not in itself a finding about the gene and the disease.
gout (continued). "In order to define over-production in IL-1β release as the major culprit for attacks of gout, production of other cytokines mediating chemotaxis of neutrophils, notably IL-8 and IL-17, should not be affected by co-incubation with C18:0 and MSU." (PMID 22762240, 2012). "In the present study, we show that PBMCs from gout patients produce more IL-1β than controls when incubated with C18:0 and MSU." (PMID 22762240, 2012). "Interleukin-1β (IL-1β) has been identified as a pivotal cytokine in gout and MSU crystal-induced inflammation." (PMID 22608202, 2012). "Given the previously suggested critical role of IL-1β in the pathogenesis of gout, we studied the possible effect of inhibition of IL-1 signaling on NET formation." (PMID 22195044, 2011). "Septic shock and autoinflammatory diseases such as vitiligo, Crohn's disease, Muckle-Wells syndrome, and gout, among others, result from overactive release of proinflammatory cytokines including IL-1β." (PMID 22241984, 2011). "Activation of NLRP3 inflammasome by MSU crystals is thought to regulate pro-IL-1β processing during gout." (PMID 22195044, 2011). "The critical role of IL-1β in the pathogenesis of gout was confirmed by the beneficial clinical outcome of IL-1β blockade in patients with gout." (PMID 22195044, 2011). "Once infiltrated in the joints, MSU crystals trigger monocytes/macrophages to produce IL-1β, a mechanism highly relevant to gout, the acute form of which is effectively treated with the recombinant form of IL-1-receptor antagonist, a specific IL-1 inhibitor." (PMID 20149224, 2010). "A comparison of patients with RA, OA, psoriatic arthritis and gout recorded the highest levels of IL-1β, IL-6, IL-8 and IDO as well as the lowest levels of tryptophan in RA synovial fluids, indicating stimulated cellular immune responses in RA patients." (PMID 16277684, 2005). "Notably, the E127Q and E127S variants significantly reduced mRNA levels of the key pro-inflammatory cytokines IL-1β and IL-6-central players in the pathogenesis of diseases such as rheumatoid arthritis, gout, and other IL-1-driven conditions." (PMID 41424853, 2026). "In gout, elevated IL-6 levels may serve as a marker for active IL-1β, as the ability of IL-1β to induce IL-6 is well-established." (PMID 41415576, 2025). "During the acute phase of gout, mature IL-1β induces the release of abundant NETs by neutrophils." (PMID 40362468, 2025). "The rs4728141 C allele was associated with increased IL-1β expression in unstimulated PBMCs of controls, but not in gout." (PMID 41155224, 2025). "Moreover, IL-6, JAK2, STAT1/3, p-JAK2, p-STAT1/3, and IL-1β proteins were markedly higher in the acute gout (AG) group compared to the intercritical gout (IG) and HC groups." (PMID 40170729, 2025). "Previous studies have exhibited that honeysuckle polysaccharides could exert anti-gout activity by downregulating the levels of inflammatory factors IL-1β, IL-6, and TNF-α in the serum of mice in a sodium urate-induced gouty arthritis model." (PMID 40942068, 2025). "Inflammation in gout is primarily an innate immune response mediated by Interleukin-1β (IL-1β)." (PMID 41155224, 2025). "Compared to baseline (0 h), both IL-1β and IL-6 protein levels were significantly elevated after 1 h (both P < 0.05), with peak inflammation observed at 4–6 h, indicating successful establishment of the acute gout inflammation model." (PMID 40170729, 2025). "Additionally, in the MSU-induced human blood ex vivo gout model over 0–12 h, IL-1β and IL-6 protein expression levels increased at 1 h and peaked between 4 and 6 h compared to baseline." (PMID 40170729, 2025). "Given that monosodium urate crystals drive gouty inflammation primarily through NLRP3 inflammasome activation and the subsequent release of IL-1β and IL-18, the suppressive effects of GDF15 on these mediators suggest a potential regulatory role in modulating gout-associated inflammatory responses." (PMID 40722837, 2025).
gout (continued). "To conclude, we find that the rs4728141 gout risk allele C is associated with a more potent inflammatory reaction in response to both palmitate and palmitate/MSU crystal combination by upregulating the IL-1β production." (PMID 41155224, 2025). "Furthermore, rs4728141 was associated with an increase in IL-1β production ratio between palmitate with MSU and palmitate alone in gout patients." (PMID 41155224, 2025). "Whole-genome sequencing studies further identify novel genetic loci (RCOR1, FSTL5-MIR4454) and transporter variants (ABCG2, SLC22A12) associated with early-onset gout, with RCOR1 promoting NLRP3 inflammasome activation and IL-1β release, which are key drivers of gouty inflammation." (PMID 40880930, 2025). "Furthermore, Compared to 12-hour gout model WT mice, IL-1β, IL-6, JAK2, STAT1/3 mRNA, protein expression, and phosphorylated protein levels were notably decreased in IL-6 KO mice." (PMID 40170729, 2025). "Moreover, IL-1β inhibitors have proven beneficial and safe for patients with pain conditions such as gout and intervertebral disc degeneration." (PMID 41276822, 2025). "Consequently, IL-1β mediates gouty arthritis and IL-1β antagonism is highly effective in treating this condition." (PMID 39496966, 2025). "IL-1β blockade with canakinumab does not affect the magnitude of these associations, while baseline kidney function and prior gout do." (PMID 39862678, 2025). "Therefore, interventions targeting inflammatory mediators, such as the use of IL-1β inhibitors, have become one of the new strategies for gout treatment." (PMID 39980931, 2025). "Mechanistically, studies have shown that dysregulation of the signaling cascade is associated with gout, while the circadian clock can regulate the expression and activation of NLRP3, thereby controlling the secretion of IL-1β and IL-18 in various tissues and immune cells, particularly macrophages." (PMID 40495130, 2025). "A ‘younger’ gut microbiota could suppress the activation of NLRP3, caspase-1, and IL-1β, thereby reducing the inflammatory response in gout." (PMID 39907694, 2025). "Furthermore, the 2-h human blood ex vivo gout inflammation model showed significantly elevated levels of IL-1β, IL-6, JAK2 mRNA, and their respective proteins, including phosphorylated JAK2 and STAT1/3, compared to both control groups." (PMID 40170729, 2025). "Combined with strategies to reduce risk factors and interventions such as fenofibrate, febuxostat, and the IL-1β-targeting monoclonal antibody canakinumab, this approach could aid in developing preventive measures to reduce the incidence of gout." (PMID 39845814, 2024). "These decreases in arthritic severity and inflammatory cell infiltration were almost completely reversed by the intra-articular injection of recombinant IL-1β into the affected joints, demonstrating the decisive role of the myeloid NCOA6–IL-1β axis in NLRP3-dependent gouty arthritis." (PMID 38195836, 2024). "The release of IL-1β, IL-18 and TNF are tightly associated with the pathogenesis of gout." (PMID 39130631, 2024). "We incubated BMDMs with IL-1β to model the gout pro-inflammatory state 4,13." (PMID 39426967, 2024). "Moreover, in the HUA and gouty arthritis models, IL-1β and TNF-α secretion into the mouse serum was significantly greater than that in the vehicle group." (PMID 38708084, 2024). "The ability of the ceRNA network to predict miRNAs and lncRNAs upstream of CXCL8, CXCL1, CXCL2, IL-1β, and IL6 may lead to the use of a novel diagnostic and prognostic marker for gout." (PMID 38686389, 2024). "Moreover, NCOA6 expression was elevated in the synovial macrophages of patients with gouty arthritis, correlating with IL-1β expression." (PMID 38195836, 2024). "Moreover, decreased HOTTIP significantly suppressed the release of pro‐inflammatory factors IL‐1β and IL‐8 in macrophages during acute gouty arthritis." (PMID 38363110, 2024).
gout (continued). "It was found that tear uric acid levels were higher in gout patients than in non-gout patients, and tear uric acid values were significantly and positively correlated with tear IL-1β levels, suggesting an interaction between gout and ocular inflammatory response." (PMID 38376774, 2024). "According to previous studies and existing mechanisms, the decreased levels of IL-38 in serum of patients with gout may be because IL-38 inhibits the action of IL-1β to prevent the occurrence and development of the disease." (PMID 39483458, 2024). "Thus, we aimed to investigate the anti-inflammatory effect of deZP, a drug used in pharmacopuncture, on NLRP3 inflammasome-derived gouty arthritis via its effect on IL-1β regulation." (PMID 39861092, 2024). "IL-1β is a key mediator that drives inflammation in gout, with the role of nod-like receptor pyrin domain containing 3 inflammasome activation being well-established during gout flares." (PMID 37491293, 2023). "In addition, a ketogenic diet (KD) can inhibit NLRP3 inflammasome activation by increasing the level of beta-hydroxybutyrate in neutrophils, thereby blocking IL-1β production and alleviating gout." (PMID 37370025, 2023). "IL-1β inhibitors may be a beneficial and safe medication for patients experiencing gout flares for whom current standard therapies are unsuitable." (PMID 37491293, 2023). "However, some studies have demonstrated an elevated IL-1β release after ATP stimulation of whole blood cells in gout patients carrying the E496A mutant compared to the normal population." (PMID 36686377, 2023). "IL-1β is an inflammatory cytokine secreted by macrophages that also plays a crucial role in gout." (PMID 37734872, 2023). "Clinically relevant therapeutic agents targeting gout-producing IL-1β have also been undertaken." (PMID 37478249, 2023). "Canakinumab, a human neutralizing monoclonal antibody to IL-1β, has been approved for the treatment of systemic inflammatory diseases such as cryopyrin-associated periodic syndrome (CAPS), systemic-onset juvenile idiopathic arthritis, and refractory gout." (PMID 37441079, 2023). "This systematic review assessed the effectiveness of IL-1β inhibitors for the management of gout flares by examining the accumulated evidence of studies published between 2011 and 2022 and represents the first systematic review of this topic in nearly a decade." (PMID 37491293, 2023). "Canakinumab, an anti-IL1B monoclonal antibody, effectively treats gout flares." (PMID 36987445, 2023). "NLRP3 inflammasome produces IL-1β in gout, composed of NLRP3, ASC, and pro-caspase-1." (PMID 37881185, 2023). "In addition, we divided the onset of gouty arthritis into acute and remission stages and then assessed the expression of serum dsDNA, IL-1β, MCP-1, TNF and IL-6." (PMID 37810893, 2023). "It is known that IL-1β is a critical inflammatory cytokine involved in gout pain and inflammation." (PMID 37464384, 2023). "Pharmacological blockage of IL-1β signaling shows profound effectiveness for attenuating gout pain." (PMID 37464384, 2023). "Several potentially eligible studies using IL-1β inhibitors for treating gout flares published prior to 2011 were therefore excluded which may have added additional evidence to this review." (PMID 37491293, 2023). "As for the importance of IL-1β in gouty inflammation whose production is mediated in an inflammasome-dependent manner, targeting IL-1β as well as the components in inflammasome pathway may provide promising avenues for therapeutic treatment of gout." (PMID 37197585, 2023). "The study showed that chaetocin inhibits IL-1β secretion, thereby providing gout relief." (PMID 36824696, 2023). "Regarding the inflammatory indicators, there was a significant increase in the levels of CRP (38.12 ± 48.46 vs. 7.55 ± 9.82, p = 0.014), IL-1β (55.92 ± 45.54 vs. 41.86 ± 32.42, p = 0.028) and IL-6 (45.89 ± 96.51 vs. 8.75 ± 6.43, p = 0.031) when the patient had an acute gout flare." (PMID 36896178, 2023).
gout (continued). "Anakinra, an IL-1 receptor antagonist that inhibits the activity of both IL-1α and IL-1β, is effective in reducing acute gout pain and inflammation and may be a reasonable option in patients with CKD." (PMID 37014501, 2023). "A recent study reported that after treatment with IL-1β, an improved excretion of uric acid in human renal proximal tubular epithelial cells (HK-2 cells) was discovered, which was similar to gout patients’ urinary urate excretion during the gout flare." (PMID 36896178, 2023). "MSU crystals then activate monocytes and macrophages, resulting in the NLRP3 (NLR family pyrin domain containing 3) inflammasome-mediated release of IL-1B and proinflammatory cytokines and recruitment of neutrophils to the site of crystal deposition, driving the clinical features of gout." (PMID 36987445, 2023). "IL-1β and IL-18 are crucial proinflammatory cytokines that play a role in the pathogenesis of gout." (PMID 36979628, 2023). "Nevertheless, this systematic literature review suggests that IL-1β-targeted therapy may be beneficial in patients with gout who are unsuitable for current standard therapies." (PMID 37491293, 2023). "The inhibition of IL-1β production is considered a therapeutic target in gout." (PMID 36354664, 2022). "Similarly, the levels of IL-1β in plasma were positively correlated with the severity of alcoholic liver injury and gouty arthritis." (PMID 36176434, 2022). "Therefore, the inhibition of NLRP3 inflammasome-mediated IL-1β production process is a new and beneficial strategy for the treatment of gout." (PMID 35047046, 2022). "Interestingly, LXA4 also significantly inhibited the expression of NLRP3, cleaved caspase-1, and matured IL-1β in the joint of gouty arthritis rats." (PMID 36569930, 2022). "Therefore, it seems reasonable that IL-1B inhibition in gout is considered when those therapeutic strategies fail or are contraindicated." (PMID 36714095, 2022). "IL-1β induced by MSU crystal promotes the recruitment of inflammatory cells, especially neutrophils, at the sites of inflammation, and triggers gouty inflammation, which is considered an important pathological hallmark of gout." (PMID 36569930, 2022). "Thus, it is important to identify these pathways and understand their interactions with the NLRP3 inflammasome and IL-1β production during the development and resolution phases of gout." (PMID 35370689, 2022). "illustrated that MicroRNA-302b could directly bind to the 3’ UTR of IRAK4 and EphA2 in an in vivo and in vitro model of gout to inhibit activation of the NF-KB pathway to reduce IL-1β." (PMID 36034424, 2022). "Gout is caused by precipitation of uric acid from the blood into insoluble monosodium urate crystals, which form during periods of hyperuricemia and activate the NOD-like receptor family pyrin domain containing-3 inflammasome resulting in secretion of IL-1β." (PMID 35726318, 2022). "Therefore, although the role of the NLRP3/IL-1β inflammatory signaling pathway in gout arthritis has been identified, its role in the overall progression of gout disease is unclear." (PMID 36569836, 2022). "Moreover, LXA4 alleviated joint inflammation and decreased the production of cleaved caspase-1 and matured IL-1β in gouty arthritis rats." (PMID 36569930, 2022). "Thus, the release of moderate amounts of IL-1β following the action of the danger signal ATP in gout contributes to the induction of self-resolution of inflammation in the organism." (PMID 36052144, 2022). "The high release of IL-1β is thought to be the first symptom of gout." (PMID 36286462, 2022). "The results showed that a combination of AP and AE reduced serum and renal IL-1β levels in hyperuricemia rats, suggesting that this treatment exerted anti-inflammatory and nephroprotective effects to prevent hyperuricemia from developing into gout." (PMID 35726318, 2022).
gout (continued). "IL-1β is unquestionably the most broadly studied cytokine of the IL-1 family and is involved in a wide range of inflammatory diseases, including RA, osteoarthritis (OA), gout, periodic fever, and type II diabetes." (PMID 36032089, 2022). "As a core cytokine of gout inflammation, IL-1β can stimulate the expression of other inflammatory factors through autocrine and paracrine ways, promote the inflammatory cascade and participate in the development of gout inflammation." (PMID 36569836, 2022). "According to the American College of Rheumatology guidelines and the BNF, IL-1β inhibitors (e.g., canakinumab) could be used for certain cases of gouty arthritis that cannot be treated with NSAIDs." (PMID 36234744, 2022). "In agreement, we find here that an MSU-induced gout attack is dependent on AT2 expression and NO release by macrophages, which may interact with TRP channels to cause IL-1β increase." (PMID 36173505, 2022). "However, as the levels of LXA4 released from our body are not enough to defeat inflammatory responses induced by harmful stimuli, the levels of IL-1β in acute gout are elevated." (PMID 36569930, 2022). "Similarly, annexin A1, a glucocorticoid regulatory protein, reduced neutrophil infiltration and IL-1β release by inducing apoptosis in neutrophils in a MSU-induced gouty arthritis mouse model." (PMID 35464445, 2022). "This study aimed to investigate the molecular mechanism of Tongfengding capsule (TFDC) in treating immune-inflammatory diseases of gouty arthritis (GA) and interleukin-1-beta (IL-1β) inhibitors by using network pharmacology, molecular docking, and cell experiments." (PMID 36193152, 2022). "Functionally enhanced P2X7R gene polymorphisms in gout patients imply a more sensitive ATP response in these populations, as evidenced by the rapid opening function of P2X7R channels and the massive release of IL-1β." (PMID 36052144, 2022). "The pathogenesis of MSU-induced gout involving these components may be initiated and amplified by IL-1β, a key regulator of gout maturated by the NLRP3 inflammasome." (PMID 35400961, 2022). "This was consistent with previous findings demonstrating IL-1β expression in patients with gout." (PMID 36139553, 2022). "Furthermore, βOHB improved NLRP3 inflammasome-mediated inflammatory diseases, such as Muckle-Wells syndrome, spinal cord injury, and gout flares, and reduced caspase-1 activation and IL-1β secretion." (PMID 35585627, 2022). "NLRP3 inflammasome inhibitors and IL-1 inhibitors, such as anakinra (an IL-1R antagonist), rilonacept (IL-1 TRAP), and canakinumab (monoclonal anti-IL-1β antibody), have been tested in clinical trials and showed efficacy in the treatment of acute and chronic gout patients." (PMID 36387275, 2022). "The resulting bioactive IL-1β stimulates the inflammation of gout and might contribute to the development of other co-morbidities." (PMID 33748660, 2021). "Given the critical function of NLRP3 activation and induction of IL-1β in the pathogenesis of diseases such as gout, these mechanisms of action suggest that LF could have utility in other diseases as well." (PMID 34583676, 2021). "IL-1β has emerged as an important indicator to assess the acute gout model." (PMID 34079466, 2021). "The leucine-rich region located at the C-terminus of the NLRP3 molecule can recognize the endogenous danger signals caused by MSU, and then MSU combines with NLRP3 to promote the activation of NLRP3 inflammasomes and drive caspase-1 to process pro-IL-1β into mature IL-1β, which leads to gout flare." (PMID 33935726, 2021). "Similarly, freshly isolated synovial fluid cells (SFCs) from five gout patients were incubated with the presence of Eri, and caspase-1 activation and IL-1β production were inhibited in all patients." (PMID 34745110, 2021). "Previous work indicated that IL-1β is primarily produced by monocytes/macrophages in gout." (PMID 33493135, 2021).